RNASET2 (ribonuclease T2)
Diseases named in the same sentence as RNASET2 in open-access papers (continued):
Sharing a sentence is not in itself a finding about the gene and the disease.
autoimmune disease (9 papers, 2019 to 2025). A disorder resulting from loss of function or tissue destruction of an organ or multiple organs, arising from humoral or cellular immune responses of the individual to their own tissue constituents. "The expression of RNASET2 has been associated with cancer, autoimmune diseases, biological stress, apoptosis, and triggering of innate immunity." (PMID 39953635, 2025). "Genome-wide association studies recently identified RNASET2 among a cluster of genes associated with increased susceptibility to develop autoimmune diseases, including rheumatoid arthritis (RA)." (PMID 39500942, 2024). "Ribonuclease T2 gene (RNASET2) variants are associated in genome wide association studies (GWAS) with risk for several autoimmune diseases, including Crohn’s disease (CD)." (PMID 36466822, 2022). "The polymorphisms of the human RNASET2 gene have been identified as a risk factor for several autoimmune diseases by a number of GWAS (Genome-wide association study) assays." (PMID 33767133, 2021). "Moreover, recent genome-wide association studies (GWAS) identified RNASET2 among novel genes associated with increased susceptibility to develop autoimmune diseases, including RA14,15." (PMID 39500942, 2024). "Moreover, dysregulation of RNASET2 expression has been associated with several pathological conditions including autoimmune diseases and cancer." (PMID 39500942, 2024). "Similarly, activation of PMNs by soluble immune complexes, a hallmark of several autoimmune diseases, also induced RNASET2-associated NETs." (PMID 39500942, 2024). "Taken together, these results propose a role for RNASET2 in the pathogenesis of autoimmune diseases." (PMID 39500942, 2024). "Strikingly, RNASET2 expression was significantly upregulated in patients with several autoimmune diseases compared to healthy controls." (PMID 37626657, 2023). "We propose that the downregulation of TMEM230 and RNASET2 may represent a paradigm for the study of age-dependent autoimmune disorders due to their role in regulating glycosylation, unfolded protein response, and PI3K-AKT-mTOR signaling." (PMID 40141059, 2025).
Leukoencephalopathy (9 papers, 2019 to 2025). This term describes abnormality of the white matter of the cerebrum resulting from damage to the myelin sheaths of nerve cells. "Lastly, the spectrum of LSDs is further widened by conditions like RNASET2-Deficient Leukoencephalopathy." (PMID 41614773, 2025). "Using this analysis, the authors identified a novel homozygous variant of c.233C > A; p.Ser78Ter in exon 4 of the RNASET2 gene compatible with the diagnosis of RNASET2-deficient leukoencephalopathy." (PMID 37626657, 2023). "This study offers valuable insights into the pathogenetic mechanisms underlying the prenatal onset of RNASET2-deficient leukoencephalopathy in humans, establishing a connection between this lysosomal disorder and the innate immune system." (PMID 37626657, 2023). "Loss of function mutations in ribonuclease T2 (RNASET2) cause early onset leukoencephalopathy resembling congenital cytomegalovirus brain infection in humans." (PMID 35646933, 2022). "Infantile-onset RNaseT2 deficient leukoencephalopathy is characterised by cystic brain lesions, multifocal white matter alterations, cerebral atrophy, and severe psychomotor impairment." (PMID 34764281, 2021). "Similar to AGS, RNAseT2‐deficient leukoencephalopathy is another severe leukodystrophy with clinical manifestations resembling a congenital cytomegalovirus brain infection." (PMID 32212285, 2020). "Although these microglial defects have not yet been described in RNAseT2‐deficient leukoencephalopathy patients, they still represent an early marker of the pathology and a potential therapeutic target for RNASET2‐deficient leukoencephalopathy." (PMID 32212285, 2020). "RNAseT2‐deficient leukoencephalopathy was already proposed to be classified as an LSD from our previous study, showing accumulation of rRNA in neurons." (PMID 32212285, 2020). "RNAseT2‐deficient leukoencephalopathy is a severe childhood white matter disorder affecting patients in their first year of life and mimicking a cytomegalovirus brain infection." (PMID 32212285, 2020). "We studied potential pathophysiological disease mechanisms of an early onset childhood leukoencephalopathy caused by loss-of-function mutations in the gene encoding the ribonuclease RNASET2." (PMID 32295832, 2020). "Like many other interferonopathies, AGS and RNaseT2-deficient leukoencephalopathy are monogenetic disorders—as such, each of the animal models previously discussed disrupt the function or expression of a single gene linked to the human condition." (PMID 33519829, 2020). "This study identified dysfunctional microglia as a new early marker of the pathology in RNAseT2‐deficient leukoencephalopathy." (PMID 32212285, 2020). "Using microglia‐specific depletion and rescue experiments, we identified microglia as drivers of this embryonic phenotype and potential key cellular player in the pathology of RNAseT2‐deficient leukoencephalopathy." (PMID 32212285, 2020). "Like many other LSDs and leukodystrophies, RNASET2‐deficient leukoencephalopathy affects patients during the early years of life, suggesting a fetal initial insult." (PMID 32212285, 2020). "On brain imaging, infants with RNASET2 deficiency predominantly reveal a leukoencephalopathy with multifocal white matter alterations, including calcifications in supratentorial but also cerebellar grey and white matter regions." (PMID 32295832, 2020). "Defective RNASET2 leads to RNASET2-deficient leukoencephalopathy, a rare autosomal recessive neurogenetic disorder with psychomotor delay as its main clinical symptom." (PMID 31349848, 2019). "Due to overlapping clinical and radiologic features of RNASET2-deficient leukoencephalopathy, AGS and congenital CMV infections, molecular study as an important and helpful diagnostic tool should be considered to avoid misdiagnosis." (PMID 31349848, 2019).
Leukoencephalopathy (continued). "To determine how the neuronal MEF2C transcription network is affected by IFN-I hyperactivation, we examined a published snRNA-seq dataset of RNaseT2−/− mice, a model of infantile-onset RNaseT2-deficient leukoencephalopathy with severe IFN-I neuroinflammation and cognitive impairment." (PMID 37095396, 2023). "This study provides a first look into the prenatal onset pathomechanisms of human RNASET2-deficient leukoencephalopathy, linking this inborn lysosomal disease to the innate immune system and other immune-related childhood encephalopathies like Aicardi-Goutières syndrome (AGS)." (PMID 32295832, 2020). "We hypothesized that the early onset of RNAseT2‐deficient leukoencephalopathy is caused by abnormal microglial activity during neurodevelopment." (PMID 32212285, 2020). "OPCs were of different interest in our study, since they develop into oligodendrocytes, the myelinating cells of the CNS that form a major part of white matter, which is mainly affected in patients with RNASET2-deficient leukoencephalopathy and a hallmark of the disease." (PMID 32295832, 2020). "Our study identifies an important role for the ribonuclease T2 protein in early brain development and reveals that deficient microglia could underpin the pathology of RNAseT2‐deficient leukoencephalopathy." (PMID 32212285, 2020). "Our results discover an unknown link between RNASET2 deficiency and the innate immune system, which also proposes a novel pathomechanism for related leukoencephalopathies like AGS." (PMID 32295832, 2020). "Recapitulating AGS and RNaseT2-deficient leukoencephalopathy phenotypes in animal models could provide crucial insights into neuropathology and invaluable preclinical therapy development." (PMID 33519829, 2020). "In addition to AGS1–7, mutations in RNASET2 have been linked to a closely related interferonopathy in human patients, with a similar neurological and inflammatory phenotype: RNaseT2-deficient leukoencephalopathy." (PMID 33519829, 2020).
leukodystrophy (8 papers, 2018 to 2024). Leukodystrophies are a group of rare, progressive, metabolic, genetic diseases that affect the brain, spinal cord and often the peripheral nerves. "RNASET2-deficient leukodystrophy is a rare infantile white matter disorder mimicking a viral infection and resulting in severe psychomotor impairments." (PMID 38753517, 2024). "As such, our findings provide further evidence that microglia are central to RNASET2-deficient leukodystrophy pathology and support a targeting of microglia as a potential therapeutic strategy." (PMID 38753517, 2024). "Nonetheless, the rescue of locomotion in transplanted animals suggests that the microglia are an attractive target for the development of future interventions in RNASET2-deficient leukodystrophy." (PMID 38753517, 2024). "In this review, we focus specifically on AGS and the closely related RNaseT2-deficient leukodystrophy." (PMID 33519829, 2020). "Crucially, these animals also fail to recapitulate the key hallmark of RNaseT2-deficient leukodystrophy pathology: white matter abnormalities." (PMID 33519829, 2020). "Here, we summarize the human phenotype of AGS and RNaseT2-deficient leukodystrophy and provide a brief overview of the human genetics involved in these disorders." (PMID 33519829, 2020). "White matter lesions, subcortical cysts and calcification are central to the pathogenesis of RNaseT2-deficient leukodystrophy, contributing to the devastating psychomotor impairments observed in the clinic." (PMID 33519829, 2020). "In summary, our study highlights a cellular mechanism whereby microglia are the drivers of RNASET2-deficient neuropathology and suggests that microglia-directed approaches may have therapeutic benefits in leukodystrophy." (PMID 38753517, 2024). "As such, this work supports the hypothesis that supplementation of healthy microglia improves aspects of pathology in RNASET2-deficient leukodystrophy and that therapeutic targeting of the microglia may represent a future treatment avenue." (PMID 38753517, 2024). "Yet, in the field of interferonopathy modeling, it seems the zebrafish—a species more evolutionarily distant from humans—arguably better recapitulates clinical phenotypes, with particular relevance to the neurological symptoms at the core of AGS and RNaseT2-deficient leukodystrophy." (PMID 33519829, 2020). "Thus, we believe discussion of RNaseT2-deficient leukodystrophy alongside AGS in the context of interferonopathy here is warranted." (PMID 33519829, 2020). "Therefore, microglia-targeted interventions may have therapeutic benefits in RNASET2-deficient leukodystrophy." (PMID 38753517, 2024). "Murine models of leukodystrophies have failed to reproduce all aspects of the human disease, with a recent RNASET2‐deficient rat model showing deficiencies in object recognition memory but no locomotor or spatial memory defects." (PMID 32212285, 2020). "Patient 9 was diagnosed as affected by RNASET2-related leukodystrophy." (PMID 30111349, 2018).
Crohn disease (7 papers, 2017 to 2025). A gastrointestinal disorder characterized by chronic inflammation involving all layers of the intestinal wall, noncaseating granulomas affecting the intestinal wall and regional lymph nodes, and transmural fibrosis. "GWAS data have confirmed an association between RNASET2 and susceptibility to vitiligo, RA, Graves’ disease, and Crohn’s disease." (PMID 39953635, 2025). "The RNASET2 locus has been implicated by GWAS in susceptibility for vitiligo, Rheumatoid arthritis, Graves’ disease and Crohn’s disease." (PMID 36466822, 2022). "Finally, after phenotype scanning, RNASET2 (rs71573407) was linked to complications of the puerperium, while RNASET2 (rs162298) was associated with Crohn’s disease, hypothyroidism or myxoedema, and treatment with levothyroxine sodium." (PMID 38576019, 2024). "Moreover, a recent single-cell RNAseq study integrating cell-specific-eQTL to RNASET2 disease risk variants provides strong evidence that multiple immune cell subsets including CD4+ T cells contribute to Crohn’s disease causation." (PMID 36466822, 2022). "For instance, RNASET2 regulated by rs1819333 is associated with inflammatory bowel diseases and crohn disease, which further illustrated that significant association of SNPs and genes in SNP‐methylation‐mRNA chains, may play a decisive role in the process of immune response in PBMCs." (PMID 31106970, 2019). "Additionally, the results of our colocalization analysis support a shared signal between the eQTL rs393727—RNASET2 in CD4 + T cells and GWAS signals for IBD (including Crohn’s disease and ulcerative colitis cases together) and more specifically only CD." (PMID 37072791, 2023).
vitiligo (7 papers, 2016 to 2025). Generalized well circumscribed patches of leukoderma that are generally distributed over symmetric body locations and is due to autoimmune destruction of melanocytes. "SCHIP1 (3q25) has been associated with SLE, while RNASET2(6q27) has been identified as a risk gene for both vitiligo and GD." (PMID 38616254, 2024). "Interestingly, a GWAS study conducted on the Chinese Han population suggested a hazardous association between vitiligo and RNASET2." (PMID 39035989, 2024). "GWAS identifies RNASET2 as a susceptible gene to vitiligo in the Chinese Han population, but the function of RNASET2 in vitiligo pathogenesis or in melanocyte apoptosis is unknown." (PMID 26870082, 2016). "Therefore, RNASET2 regulates the oxidative stress and intervenes the initial pathogenic event in melanocyte destruction in vitiligo." (PMID 26870082, 2016). "In contrast, enhanced levels of RNASET2 is are detected in vitiligo patient specimens and can be induced in vitro in cultured primary human melanocytes and keratinocyte in response to stress." (PMID 36466822, 2022). "Hence, RNASET2 may contribute to vitiligo pathogenesis by inhibiting TRAF2 expression." (PMID 26870082, 2016).
Aicardi-Goutières syndrome (6 papers, 2018 to 2026). "Additionally, it highlights the potential links between RNASET2 deficiency and other immune-related childhood encephalopathies such as Aicardi-Goutières syndrome (AGS)." (PMID 37626657, 2023). "Moreover, there is a significant clinical, biochemical and neuroradiological overlap of RNASET2-deficient cystic leukoencephalopathy with Aicardi-Goutières syndrome (AGS) in some affected individuals." (PMID 32295832, 2020).
melanoma (6 papers, 2020 to 2024). A malignant, usually aggressive tumor composed of atypical, neoplastic melanocytes. "Examples of such genes are: RNASET2, a known tumor antagonist in melanoma; and FCRL1, encoding a glycoprotein linked to the disease’s progression." (PMID 33704427, 2021). "For example, RNASET2 acts as a tumor suppressor in colorectal cancer, melanoma, non-Hodgkin's B-cell lymphoma, and acute lymphoblastic leukemia." (PMID 38576019, 2024). "Several studies documented that RNASET2 plays a vital role as a tumor suppressor gene in the progression of ovarian tumors and melanomas." (PMID 36728187, 2023). "For example, RNASET2 expression decreased both in ovarian tumors and melanoma and it was negatively correlated with the malignancy of these tumors." (PMID 36728187, 2023). "RNASET2 was also a tumor antagonizing gene in the melanoma model." (PMID 32528897, 2020). "It was reported that RNASET2 protein expression was reduced in several melanoma cells." (PMID 32528897, 2020). "Colocalization results found that RNASET2 was highly colocalized with non-epithelial skin cancer in both the UKB-PPP (PP.H4 = 0.973) and deCODE (PP.H4 = 0.939) studies but not with melanoma." (PMID 39035989, 2024).
colon carcinoma (5 papers, 2015 to 2025). "Noteworthy, a murine Rnaset2 syngeneic murine model was also recently reported by using mouse Rnaset2-overexpressing C51 colon carcinoma and TS/A mammary adenocarcinoma syngeneic cells in comparison to control empty vector-transfected tumor cells." (PMID 36012339, 2022). "Taken together, these data prompted us to further investigate the oncosuppressive potential of murine Rnaset2 using the less aggressive colon cancer-derived C51 cell line." (PMID 32197460, 2020). "And human recombinant RNASET2 disrupted angiogenesis and inhibited clonogenicity of colon cancer cells." (PMID 32528897, 2020). "Similar results were also reported for human colon cancer cells treated with the RNASET2 fungal ortholog ACTIBIND." (PMID 25797262, 2015). "In addition, the role of RNASET2 in colon cancer has also been reported." (PMID 32528897, 2020).
lung carcinoma (5 papers, 2019 to 2024). "A meta-analysis revealed a correlation between RNASET2 and an elevated risk of lung cancer." (PMID 38576019, 2024). "Furthermore, genome-wide association analysis revealed a new locus of RNASET2 heterogeneity in genetic susceptibility associated with lung cancer risk, implying RNASET2 may function as a lung cancer suppressor gene." (PMID 32528897, 2020). "The study identified RNASET2, SECISBP2L,NRG1, CHRNA2, OFBC1 and RTEL1 as candidate genes associatedwith lung cancer." (PMID 33959694, 2020). "This study highlighted the genetic heterogeneity across histological subtypes of lung cancer and reported novel loci for lung cancer at 1p31.1 (rs71658797, FUBP1), 6q27 (rs6920364, RNASET2), 8p21.1 (rs11780471, CHRNA2), and 15q21.1 (rs66759488, SEMA6D)." (PMID 31069257, 2019).
gastric adenocarcinoma (4 papers, 2020 to 2023). "For example, in ovarian cancer, gastric adenocarcinoma and melanoma, downregulation of RNASET2 significantly enhanced the malignant phenotype of the tumor and correlated with a worsening of the patient’s clinical outcome." (PMID 37679715, 2023). "TCGA stomach adenocarcinoma data (Nature 2014, 173 cases of intestinal type and 65 cases of diffuse type) also confirmed that the expression levels of RNASET2 mRNA were lower in diffuse type GAC than that in intestinal type GAC (p = 0.0048)." (PMID 32528897, 2020). "RNASET2 was downregulated in gastric adenocarcinoma, and the expression of RNASET2 could be performed as a biomarker for detecting the early stage of gastric adenocarcinoma." (PMID 35938021, 2022). "However, the role of RNASET2 in gastric adenocarcinoma (GAC) remains unclear." (PMID 32528897, 2020). "However, a recent study showed that RNASET2 was downregulated in the early stage of gastric adenocarcinoma compared with adjacent noncancerous or normal gastric mucosa tissues, but the knockdown or knockout of RNASET2 did not significantly promote gastric adenocarcinoma cell growth." (PMID 36728187, 2023).
Graves disease (4 papers, 2016 to 2025). Graves' disease is an autoimmune disorder that leads to overactivity of the thyroid gland (hyperthyroidism).It is caused by an abnormal immune system response that causes the thyroid gland to produce too much thyroid hormones. "RNASET2 has been correlated with Graves’ disease, an autoimmune disorder featuring hyperthyroidism, as revealed in a previous genome-wide association study." (PMID 36544093, 2022).
Autoimmunity (3 papers, 2023 to 2025). The occurrence of an immune reaction against the organism's own cells or tissues. "For instance, IFN alpha and gamma regulate ER dependent function in antigen presentation, suggesting that the TMEM230/RNASET2/SDC2/IRF1 axis is mis regulated both in autoimmunity and cancer." (PMID 40862725, 2025). "TMEM230, RNASET2 and IFNs regulate antigen processing, trafficking and presentation in autoimmunity." (PMID 40862725, 2025).